IFNG (interferon gamma)
Diseases named in the same sentence as IFNG in open-access papers (continued):
Sharing a sentence is not in itself a finding about the gene and the disease.
breast cancer (continued). "For MLKL gene expression, IFNγ upregulates MLKL mRNA in breast carcinoma and cervical carcinoma cells, and IRF1 or STAT1 knockout reverses IFNγ-mediated induction of the MLKL mRNA level." (PMID 38671928, 2024). "A higher expression of IFNG was found in the TNBC subgroup of the METABRIC cohort, as compared to other breast cancer samples (p-value < 2.2 × 10−16)." (PMID 38201582, 2023). "The relationship between the vital signature gene IFNG expression and CD8+ T cell infiltration in the breast cancer microenvironment was further analyzed." (PMID 37154982, 2023). "The use of both interferon-gamma (IFN-γ) and anti-HER2 antibodies synergistically produces a reduction of tumor growth in HER2-expressing breast cancers." (PMID 37190205, 2023). "Basal and TNBC subtypes of breast cancers overexpressed CD274 conjointly with three ferroptosis drivers: TNFAIP3, IFNG and IDO1 (IDO1: inhibitory immune checkpoint)." (PMID 38201582, 2023). "Recently, we have designed a set of Semliki Forest virus (SFV) and Sindbis virus (SIN) vectors producing proinflammatory cytokines and peptides (IL12, IFNγ, TNFα, anti-TGF-beta peptides), and confirmed their antitumour potential in mouse breast cancer model." (PMID 35804458, 2022). "Database mining revealed T‐BET was significantly correlative with IFNγ, perforin and other molecules in TNBC and breast cancer." (PMID 35894707, 2022). "CCL22 production by tumor cells was identified as a mechanism of immune escape in breast cancer, through CCR4+ Treg recruitment in the tumor microenvironment (TME), induced by IFNγ exposure." (PMID 35794623, 2022). "Contrasting the TA-MFP, mammary tumors from aged control and young DIO mice were underrepresented for immune-related gene sets(i.e., Inflammatory Response, Allograft Rejection, and IFNG Response), relative to young control mice." (PMID 36686775, 2022). "Using univariate Cox regression analysis, a total of 4 autophagy-related genes (EIF4EBP1, IFNG, NRG1, TP63) were significantly correlated with overall survival (OS) of breast cancer." (PMID 35480110, 2022). "IFNγ upregulates ISG15 and promotes ISGylation in breast cancer cells, which occurs in parallel with changes in the morphology of breast cancer cells." (PMID 36319753, 2022). "In the 4T1 breast cancer model, a higher frequency of CD4+ and CD8+ T cells producing IFNγ, TNFα, or IL-2 was found in mice treated with T. usneoides." (PMID 36358804, 2022). "We found that classical Th1 cytokines, interferon-gamma (IFN-γ) and tumor necrosis factor-alpha (TNF-α), mediated the antitumor effect of TSLP-activated CD4+ T cells against advanced breast cancer through the induction of cellular senescence." (PMID 36467403, 2022). "The results indicated that EMC2, G6PD, FLT3, IFNG, ANO6, and SLC1A4 were positively correlated with ferroptosis while CISD1, TP63, and BRD4 were negatively correlated with ferroptosis in breast cancer." (PMID 34222241, 2021). "The specific T cell reactivity restores the antitumor immunity in patients with breast cancer, which is affected by release of local cytokine and chemokines like CXC10, CXC9, IFNγ, IL-4 and IL-5." (PMID 33957948, 2021). "IFNγ and FOXP3 expressions were detected in cells cocultured with CD4 T cells and breast cancer cells." (PMID 34659411, 2021). "TNFAIP3 was strongly associated with the infiltration of all types of immune cells in breast cancer, and CXCL10 and IFNG behaved similarly in all immune cell types except macrophages." (PMID 33102239, 2020). "According to reports, increased AIM2 inflammasome expression induced by interferon-γ (IFNγ) promotes apoptosis via the mitochondrial pathway and the regulation of proapoptotic proteins in MCF-7 breast cancer cells." (PMID 32397236, 2020). "A study showed that a combination of interferon gamma (IFN-γ) and anti-HER2 antibody synergistically reduce tumor growth in mammary tumor models." (PMID 31665051, 2019).
breast cancer (continued). "The combination of the genes IFNG, CXCL13, CD30, and PRF1 clearly predicted favorable outcome in III and IV stage ovarian cancer and in basal-like breast cancer." (PMID 31998644, 2019). "As with human breast cancer cell lines, priming of MMTV-Neu cells with guadecitabine enhanced both MHC-I and MHC-II expression after IFNγ stimulation in a dose-dependent manner." (PMID 29339738, 2018). "Our data demonstrates that Mam-A DNA vaccination in advanced breast cancer patients induced activation of CD8 T-cells and upregulation of the intracellular expression of all these three effector molecules, namely, IFNγ, TNFα, and perforin." (PMID 28304339, 2017). "Research has suggested that interferon gamma (IFN-γ), an immune potentiating agent, favours activation of mitochondrial-operated apoptotic pathway in breast cancer cell lines by interacting with its receptor, interferon gamma receptor 1 (IFNGR1)." (PMID 28479926, 2017). "Thus, we speculate that breast cancer cells might also express IFNγ." (PMID 29156701, 2017). "In a study of 87 locally advanced HER2 breast cancer patients treated with trastuzumab, 94 % of the patients with high HER2 specific interferon gamma (IFN-g) Th1 immunity had pCR as compared to 33 % of patients that did not achieve pCR (p = 0.0002)." (PMID 27777769, 2016). "In the 4T1 breast cancer mouse model, gemcitabine treatment also reduces splenic MDSC accumulation, which results in increased proliferation and IFNγ production by splenic lymphocytes upon antigen stimulation compared to untreated mice." (PMID 26500653, 2015). "In particular, IFNγ, leptin, TGFβ1, TIMP1, TIMP2, thrombopoietin and VEGF levels were significantly inhibited by anandamide in the conditioned medium of MDA-MB-231 breast cancer cells." (PMID 25147760, 2014). "In the same study, PGE2 suppressed IFNγ-induced CXCL9 levelsin MCF-7 and MDA-MB 231 breast cancer cells, and COX inhibitors increased CXCL9secretion." (PMID 24004819, 2013). "In ER- breast cancer, those characterized with high expression of EGFR and low expression of Th1-mediated pathway-related markers such as interleukin-12 and interferon-gamma were found to have a poor prognosis." (PMID 22420471, 2012). "They found that 5/7 (71%) of the HLA-A2+ breast cancer patients and 6/11 (55%) of the HLAA2+ healthy controls had T cells that were reactive to SSX2 peptide p103–111 by IFNγ-ELISPOT assay." (PMID 20981248, 2010). "In ER- breast cancer, we observed that IL12 (or IFNG) synergized with TGFB to provide a better prognostic model than either pathway considered separately." (PMID 21050467, 2010). "We also verified that Th1 (IL12, IFNG) and Th2 (TGFB) modules retained the same prognostic power in multivariate models including E2F3, itself strongly prognostic in ER+ breast cancer but only marginally so in ER negatives." (PMID 21050467, 2010). "SOCS-1 has been shown to be critical for preventing interferon γ (IFNγ)-mediated growth arrest of M-1 myeloid cells, and overexpression of SOCS-1 or SOCS-3 in breast cancer lines inhibits the antiviral and antiproliferative ability of IFNγ." (PMID 12888825, 2003). "Despite the clinical signs, which resemble the presence of acute inflammation, IBCs produce inflammatory cytokines (such as IFNG, TNF, IL1A, IL1B, and IL8) at similar levels to other breast cancer subtypes, while the host inflammatory cell infiltration is low in the IBC stroma." (PMID 39103878, 2024). "Similarly, when co-cultured with breast cancer cells, it was found that CD8+CD69+CD103+TRM exhibited higher levels of IFNG and tumor necrosis factor-alpha (TNF-α) compared to CD8+CD69+CD103−T cells, further mediating a more significant tumor-killing effect." (PMID 38553708, 2024). "To test this hypothesis, we initially examined the PDL1 levels in various breast cancer cell lines and found that all the TNBC cells tested showed higher basal and IFNγ-induced expression of PDL1 than MCF7 (ER+), as expected." (PMID 38730475, 2024).
breast cancer (continued). "In support of this idea, in a recent study using a breast cancer metastasis model, MMTV-PyMT, it was shown that combined use of monophosphoryl lipid A (MPLA) and IFNγ reduced primary tumor growth and metastasis by activating a collaborative innate-adaptive immune response." (PMID 36765715, 2023). "Lastly, hormone deprivation did not influence IFNγ-induced MHC-I expression in the MDA-MB-231 breast cancer cells that do not express ER." (PMID 37450351, 2023). "In an RCT involving early-stage breast cancer patients, 8 weeks of MBSR promoted significantly better NK cell activity and lower levels of TNFα, IL-6, and interferon gamma (IFNγ) compared to the control group, who participated in a series of cancer recovery and health education classes (n = 124)." (PMID 35682203, 2022). "Furthermore, elevated IDO expression in MDSCs in breast cancer mediates immunosuppressive effects on T cells by reducing CD8+ T cell proliferation and blocking interferon‐gamma (IFN‐γ) production." (PMID 35762299, 2022). "As expected, phenformin increased the extracellular acidification rate (ECAR) in breast cancer cells, yet no further differences were measured upon co-treatment with IFNγ." (PMID 34083537, 2021). "Besides, researchers analyzed the gene expression data of invasive breast cancer tissues and proved that the JAK/STAT1 pathway activated by IFNγ was positively correlated with PD-L1 expression." (PMID 34365463, 2021). "IFNγ treatment neither increased ROS levels in breast cancer cells nor potentiated phenformin-induced ROS production." (PMID 34083537, 2021). "Breast cancer cells expressing NQO1 shRNAs are not further sensitized to IFNγ and phenformin co-treatment, suggesting that NQO1 is an essential target gene that confers the antitumorigenic effects of phenformin." (PMID 34083537, 2021). "IFNγ and phenformin also cooperatively elicit antitumorigenic responses in murine ErbB2+ (NOP6, NOP23, and NIC) and human breast cancer cell lines representative of ER+/HER2− (MCF7), HER2+ (HCC1954, BT474), and triple-negative (MDA-MB-231, BT20, MDA-MB-436, Hs578T, and BT549) disease." (PMID 34083537, 2021). "Bioinformatic analysis in breast cancer has shown that high expression of IL-12/STAT4 axis molecules, such as the IL-12 receptor genes (IL-12RB1 and IL-12RB2), STAT4, IFNγ, and TBX21, significantly increases the survival rates of patients with breast cancer, especially the more aggressive subtypes." (PMID 33076315, 2020). "Besides TMB and the expression levels of IFNγ and PD-L1 as dynamic biomarkers for ICB therapy in breast cancer, multi-gene based assays to develop combinational ICB biomarkers are required." (PMID 32258038, 2020). "Specifically, IFNγ levels were higher in noncancer controls than in patients with breast cancer, regardless of the chemotherapy status." (PMID 32703187, 2020). "Furthermore, cell from normal mammary epithelium and breast cancer cell lines expressed ICAM1 upon stimulation with the proinflammatory cytokines TNFα, IL1β and IFNγ." (PMID 30082828, 2018). "Although MT/Shc2F/2F breast cancer cells display reduced Y705-STAT3 phosphorylation in vitro, progressively growing MT/Shc2F/2F tumours (PD) that evolved in an immunocompetent background hyperactivated STAT3 compared with those that emerged in IFNγ−/− mice." (PMID 28276425, 2017). "We detected that MDA-MB-231 (tumorigenic metastatic breast cancer line) expressed a higher mRNA level of IFNγ than MCF-10A (non-tumorigenic breast tumour cell line)." (PMID 29156701, 2017). "Th1 cell production of the cytokines interferon gamma (IFNγ) and TNFα can enhance MHC class I expression, PD-L1 expression, augment apoptosis and tumor senescence, and enhances growth inhibition of many anti-breast cancer agents, including anti-estrogens and HER-2 targeted therapies." (PMID 27766079, 2016).
breast cancer (continued). "The CTLs lysed MCF-7 breast cancer cells (MUC1+, HLA-A*0201), produced IFNγ, and showed cross-reactivity with the native P1:STAPPVHNV peptide, suggesting these analog peptides may offer substantial improvements in the design of epitope-based vaccines." (PMID 27367740, 2016). "Moreover, high levels of IL12A mRNA in human breast cancer samples correlates with expression of DC-related transcription factors and GRZMB, CD8A, and IFNγ expression, suggesting an active anti-tumor T cell response." (PMID 26500653, 2015). "The mammary carcinoma T cells do not appear to be activated, since they did not produce IFNγ (data not shown)." (PMID 21846333, 2011). "When mammary tumors were pretreated with image-guided fractionated radiation therapy (IGRT) followed by anti-TAG72-IL-2 therapy, an improved tumor growth inhibition was observed along with an increased tumor infiltration of IFNγ+ CD8+ T cells and a significant reduction in Foxp3+ CD4+ cells." (PMID 40361381, 2025). "In addition, the cytolytic function of CAR MUC1 T cells was evaluated in primary breast cancer, in which both CAR MUC1 constructs demonstrated a specific antitumor activity and increased interferon gamma and IL-2 secretion after coculturing with MUC1+ primary cells." (PMID 36457849, 2022). "As an example, the activation of IFNG, an activatory target of chronic granulomatous disease, was predicted to lead to therapeutic effects on rheumatoid arthritis (RA), Parkinson’s disease (PD), type I diabetes mellitus (T1DM), acute myeloid leukemia (AML) and breast cancer (BC)." (PMID 35758779, 2022). "However, as IFNγ does not stimulate ROS production in breast cancer cells, we focused on differentially expressed genes that function as ROS scavengers." (PMID 34083537, 2021). "IFNγ treatment had no impact on breast cancer cell viability following glucose deprivation, suggesting that IFNγ signaling does not alter the glucose dependency of breast cancer cells." (PMID 34083537, 2021). "Interestingly, MORC4 expression was selectively induced by IL‐4, whereas it was not affected by IFNγ, LPS, or a co‐culture with different breast cancer cell lines." (PMID 33377644, 2020). "In an orthotopic HER2+ murine breast cancer model, tetratherapy induced high levels of antigen-specific T cell responses, tumor CD8+ T cell/Treg ratio, and augmented the presence of IFNγ- or TNFα-producing CD8+ T cells and IFNγ/TNFα bifunctional CD8+ T cells with increased cytokine production." (PMID 33747894, 2020). "Interestingly, IFNγ did not change the ability of breast cancer cells to cross the BBB, nor did it change the permeability of the BBB itself." (PMID 29350274, 2018). "We also determined that the native peptide P1:STAPPVHNV was not immunogenic for normal T cells in vitro (based on the MCF-7 cell line) but was highly immunogenic for breast cancer T cells and that the lytic activity did not always correlate with the IFNγ production." (PMID 27367740, 2016). "In addition, Ad-MGBA-infected DC-stimulated CD8+ CTLs showed a high level of IFNγ secretion when stimulated with HLA-A33+/MGBA+ breast cancer MDA-MB-415 cells, but not when stimulated with HLA-A33−/MGBA+ HBL-100 and HLA-A33−/MGBA−MDA-MB-231 cells." (PMID 23650543, 2013). "Furthermore, this p21 location has been related to breast cancer resistance to the TNF-α apoptotic effect, and it could be explained by the IFNγ effects mediated by TNFRI." (PMID 17697357, 2007). "Notably, when testing the IFNγ+ signature score between immune high and low cluster tumors, immune high tumors had significantly higher signatures scores irrespective of the breast cancer subtype (HR+ HER2− Mann-Whitney test, P-value = 6.3×10− 62, TN Mann-Whitney test, P-value = 1.3×10−18)." (PMID 39149486, 2024).
breast cancer (continued). "Consequently, CD8+ T-cell effector (Teff) score, comprising gene expression of IFNG, PRF1, CD8A and CD8B, and BATF3-DC score, calculated with the expression level of BATF3, IRF8, THBD, CLEC9A, and XCR118 were markedly increased in the high SLAMF6 group than in the low SL AMF6 group in breast cancer." (PMID 38287061, 2024). "Indeed, similar ECAR values were observed in breast cancer cells irrespective of whether they were treated with IFNγ or retained an intact STAT1 pathway." (PMID 34083537, 2021). "However, in human breast cancer or hematological cancer no changed IFNγ expression or STAT-1 signaling in MDSCs could be observed." (PMID 33072086, 2020). "We selected a low concentration of IFNγ (1 ng/mL) that induces STAT1 transcriptional responses (β2M, Tap1) but does not impair breast cancer cell growth." (PMID 34083537, 2021). "E0771 mammary tumor growth was significantly accelerated in the HFD offspring, and a reduction in the numbers of GZMB and non-significant reduction of interferon γ (IFNγ) secreting CD8+ T cells in the TME was seen." (PMID 32580156, 2020). "STAT1, but not STAT3, increased basal (MT/Shc313F/313F) and IFNγ-inducible (MT/ShcA+/+; MT/Shc2F/2F) surface MHC class I expression on breast cancer cells." (PMID 28276425, 2017). "Hence, we incubated breast cancer cell lines (MDA-MB-453, MDA-MB-231 and MCF7) as well as non-malignant SVGA cells with IFNγ for 48 h." (PMID 40469103, 2025). "Using qPCR we could show that endogenous IFNA and IFNB was expressed at very low levels in the breast cancer cell line SUM159, but not in MDA-MB-231 cells, whereas IFNG was more expressed in MDA-MB-231 cells." (PMID 37404831, 2023). "IFNγ-induced ISGylation of nonmuscle myosin II A (NMIIA) and Ras GTPase-activating-like protein 1 (IQGAP1) is involved in cytoskeletal reorganization, suggesting the role of ISGylation in the invasion and metastasis of breast cancer cells." (PMID 36319753, 2022).